RN7SL795P (RNA, 7SL, cytoplasmic 795, pseudogene)
Gene: Miscellaneous RNA gene on chromosome 18 (70,512,727 to 70,513,008, forward strand). Ensembl gene ENSG00000239748.
Homologues: Orthologues: chimpanzee Metazoa_SRP (99% identical), macaque Metazoa_SRP (89% identical). Paralogues in human: RN7SL1 (85% identical), RN7SL2 (85% identical), RN7SL3 (84% identical), RN7SL45P (83% identical), RN7SL126P (81% identical), RN7SL296P (81% identical), RN7SL218P (81% identical), RN7SL230P (81% identical), RN7SL597P (81% identical), RN7SL769P (81% identical), RN7SL118P (80% identical), RN7SL566P (80% identical), and 702 more.